PRNCR1 (prostate cancer associated non-coding RNA 1)
Synonyms: CARLo-3; PCAT8
Gene: Long non-coding RNA gene on chromosome 8 (127,079,874 to 127,092,600, forward strand). Ensembl gene ENSG00000282961.
Diseases named in the same sentence as PRNCR1 in open-access papers:
PRNCR1 is named in the same sentence as 27 diseases in open-access papers, as found by Europe PMC text mining. Sharing a sentence is not in itself a finding about the gene and the disease. The quoted sentences say what the papers report.
prostate carcinoma (43 papers, 2013 to 2025). A carcinoma that arises from epithelial cells of the prostate gland. "Recent reviews position PRNCR1 (Prostate cancer non-coding RNA within lncRNA–miRNA networks linked to apoptosis and inflammation in AKI." (PMID 41303683, 2025). "Prostate Cancer Non-Coding RNA 1 (PRNCR1) was implicated predominantly in prostate cancer, where it modulates androgen receptor activity and induces tumor growth, recent findings show that PRNCR1 is also involved in CRC." (PMID 40243746, 2025). "For instance, the lncRNA_1086.1, lncRNA_2340.1, and lncRNA_14550.3 shared homology with the human prostate cancer-associated lncRNA (PRNCR1), HOXA-AS3 lncRNA, and the predicted lncRNA TCONS-00241516, respectively." (PMID 40538732, 2025). "We evaluated the association between prostate cancer non-coding RNA 1 (PRNCR1) polymorphisms and the risk of developing gastric cancer (GC) and GC subgroups in Korea." (PMID 31288430, 2019). "Accordingly, PCGEM1 and PRNCR1 were implicated in progression of prostate cancer (PCa) as transcriptional co-regulators of the androgen receptor (AR)." (PMID 25744782, 2015). "PRNCR1, a 13-kb long noncoding RNA that is transcribed from chromosome 8q24, is involved in maintaining prostate cancer susceptibility." (PMID 26110379, 2015). "Prostate cancer-associated long-noncoding RNA 1 (PRNCR1) and PCa gene expression marker 1 (PCGEM1) are highly expressed in CRPC and known to be involved in the AR signaling pathway; however, knockdown of either PRNCR1 or PCGEM1 inhibited the growth of CRPC cells in vivo." (PMID 36902032, 2023). "rs1456315 in lncRNA prostate cancer non-coding RNA (PRNCR1) increases CRC risk." (PMID 37888204, 2023). "In addition to prostate cancer, polymorphisms in PRNCR1 at the 8q24 locus are also associated with gastric, colorectal, and lung cancer risk, indicating its functional role in multiple cancers." (PMID 34946977, 2021). "Prostate cancer non-coding RNA 1, a lncRNA transcribed from 8q24, participates in the carcinogenesis of prostate cancer (PCa) by activating androgen receptor (AR); in addition, polymorphisms of the lncRNA PRNCR1 were noted in many cancers, including colorectal cancer, prostate cancer, and GC." (PMID 32117633, 2020). "Previous studies found that PRNCR1 plays a vital role in the development of prostate cancer predisposition and it might be pivotal in prostate cancer progression by modifying androgen receptor (AR) function." (PMID 31487296, 2019). "Many SNPs of PRNCR1 are associated with prostate cancer susceptibility." (PMID 29299175, 2017). "The third region is at the location of PRNCR1 a known lncRNA also associated with prostate cancer." (PMID 24937006, 2014). "Here, we sought to evaluate whether PCGEM1 and PRNCR1 are associated with prostate cancer." (PMID 24727738, 2014). "Similarly, PCGEM1, PCA3 or PRNCR1 are three lncRNAs exclusively associated with prostate cancer." (PMID 23887658, 2013). "Two lncRNAs, PRNCR1 and PCGEM1, are found to be overexpressed in different prostate cancers and cause the androgen receptor (AR)–associated transcriptional mechanisms to induce the growth of prostate cancer." (PMID 36359888, 2022). "For example, PCA3, PCGEM1, and PRNCR1 are highly expressed in prostate cancer, while differential HULU expression is related to liver cancer and liver metastasis." (PMID 36389111, 2022). "Another small case-control study using 178 prostate cancer patients and 180 BPH cases in the Iranian population identified rs13252298, rs1456315, and rs7841060 SNPs in PRNCR1 to be associated with prostate cancer risk." (PMID 34946977, 2021). "For example, Cluster77 contains four lincRNAs, PCAT1 involved in prostate cancer development, PCAT2 associated with prostate cancer, PRNCR1 associated with include prostate disease and prostate cancer." (PMID 34906173, 2021).
prostate carcinoma (continued). "Here we show that the 8q24 prostate cancer rare variant, rs72725854 is present in an enhancer and regulates multiple lncRNAs genes namely, PCAT1, PRNCR1, PVT1, and proto-oncogene MYC in the region." (PMID 32680982, 2020). "Previous studies have observed up-regulation of PRNCR1 expression in prostate cancer cell lines and in the precursor lesion prostatic intraepithelial neoplasia." (PMID 33374332, 2020). "For example, the expression of lncRNA PRNCR1 was elevated in the urine samples of prostate cancer patients, rendering it a fine non-invasive indicator of prostate cancers." (PMID 31608229, 2019). "It has been stated that PRNCR1 is involved in the development of prostate cancer by activating androgen receptor (AR)." (PMID 29802154, 2018). "With the development of high throughput chip and sequencing technology, a variety of lncRNAs have been investigated, e.g. HOX transcript antisense RNA (HOTAIR), prostate cancer non-coding RNA1 (PRNCR1), RNA polymerase II polypeptise E gene (POLR2E)." (PMID 28159929, 2017). "For PRNCR1, we also observed that major studies were from Chinese population (67%), and four studies were involved in prostate cancer." (PMID 28159929, 2017). "For PRNCR1 rs1016343, in stratified analyses by cancer type, increased risks were observed for prostate cancer in all models (dominant model: 1.39, 1.12-1.71, 0.012; recessive model: 1.83, 1.53-2.18, 0.855; additive model: 1.42, 1.29-1.56, 0.257)." (PMID 28159929, 2017). "PRNCR1 expression is increased in prostate intraepithelial neoplasia and prostate cancer, whereas tumour cell viability and androgen receptor activity is decreased when PRNCR1 is silenced." (PMID 29299175, 2017). "A more recent study by Prensner and colleagues, however, refutes that PCGEM1 and PRNCR1 interact with the androgen receptor and that either gene is a component of androgen receptor signaling or is involved in castration-resistant prostate cancer." (PMID 25849966, 2015). "Of the long noncoding RNAs involved in prostate carcinogenesis, PCGEM1 and PRNCR1 (prostate cancer noncoding RNA1) have been identified as playing critical roles via coordination with AR." (PMID 26110379, 2015). "Given the low support for PRNCR1 in the RNA-seq data, we next confirmed these findings using quantitative PCR (qPCR) in a large set of prostate cancer tissues including 34 PCAs and 31 CRPC tumors as well as 18 benign adjacent tissues." (PMID 24727738, 2014). "While PCGEM1 has been observed in prostate cancer previously, PRNCR1 is a poorly characterized transcript, and we were concerned that PRNCR1 had been nominated by previous global profiling studies of prostate cancers." (PMID 24727738, 2014). "In summary, we have been unable to show a convincing role for PCGEM1 or PRNCR1 in aggressive prostate cancer or AR signaling." (PMID 24727738, 2014). "PRNCR1 (prostate cancer non-coding RNA1) expression was upregulated in some of the prostate cancer cells as well as precursor lesion prostatic intraepithelial neoplasia and considered as a tumor marker." (PMID 23443164, 2013). "Recently, a novel lncRNA, named PRNCR1, has been discovered and was reported to be up-regulated in prostate cancer." (PMID 24330491, 2013). "The lncRNA, termed prostate cancer non-coding RNA 1 (PRNCR1), was reported to be involved in the carcinogenesis of prostate cancer." (PMID 24330491, 2013). "PRNCR1 is an lncRNA located on chromosome 8q24.21 and is a popular oncogene in prostate cancer." (PMID 37888204, 2023). "Increasing researches have emerged that PRNCR1 could facilitate various human tumors, such as prostate cancer and colorectal cancer." (PMID 31912882, 2020). "Furthermore, prostate cancer non-coding RNA 1 (PRNCR1), which is transcribed from 8q24 region, has been displayed as a deciphered gene of human prostate cancer and is an oncogene in various diseases, such as colorectal cancer and NSCLC." (PMID 31912882, 2020).
prostate carcinoma (continued). "LncRNA Prostate cancer non-coding RNA (PRNCR1) is downregulated in many types of cancer." (PMID 31487296, 2019). "Of interest, DOT1L was recently shown to methylate non-histone proteins like the androgen receptor through recruitment of the PRNCR1 long non-coding RNA for subsequent activation of this receptor in prostate cancer after looping between enhancer and promoter sequences." (PMID 28804523, 2017). "Besides, we found that lncRNA PRNCR1 also have been widely investigated in the development of cancer, and PRNCR1 firstly identified and named in prostate cancer." (PMID 28159929, 2017). "Its inhibition attenuates the viability of prostate cancer cells and decreases the transactivation activity of AR, which indicates that PRNCR1 could be involved in prostate carcinogenesis through an AR-mediated pathway." (PMID 26110379, 2015). "Next, an independent analysis of 235 high-risk prostate cancer tissues demonstrated that neither PCGEM1 nor PRNCR1 is associated with aggressive prostate cancer, and neither lncRNA stratifies prostate cancer-specific mortality." (PMID 24727738, 2014). "Through a comprehensive analysis of RNA-sequencing data (RNA-seq), we find evidence that PCGEM1 but not PRNCR1 is associated with prostate cancer." (PMID 24727738, 2014). "First, we asked whether PCGEM1 and PRNCR1 are highly overexpressed in aggressive prostate cancer, as suggested by others." (PMID 24727738, 2014). "First, our data analysis of numerous human prostate cancer tissues from multiple independent laboratories indicates that neither PCGEM1 nor PRNCR1 are associated with castration-resistant prostate cancer." (PMID 24727738, 2014). "PCGEM1 is upregulated in clinically localized cancer, confirming the known literature; however PRNCR1 expression does not demonstrate a convincing association with prostate cancer." (PMID 24727738, 2014). "Recently, two lncRNAs, PCGEM1 and PRNCR1, have been suggested in prostate cancer to act as mediators of castration-resistance disease by binding, in a direct and sequential fashion, to the androgen receptor (AR), causing ligand-independent activation of its gene expression programs." (PMID 24727738, 2014). "Using an independent validation cohort of tissues we verified that neither PCGEM1 nor PRNCR1 is associated with aggressive prostate cancer." (PMID 24727738, 2014). "PRNCR1 was reported to have high expression in aggressive prostate cancer and was reported to enhance both ligand-dependent and ligand-independent AR-mediated transcriptional activity by directly binding to the region of 549-623 amino acids of AR and therefore promotes prostate cancer growth." (PMID 34946977, 2021). "Together, these chromatin-conformation data suggest that the rs72725854-harboring enhancer forms a spatial network with PCAT1, PRNCR1, PVT1, and MYC genes in 3D nuclear space in prostate cancer cells." (PMID 32680982, 2020). "PRNCR1 also known as PCAT8, was highly expressed in prostate cancer, and can mediate the prostate cancer cells gene activation programs and proliferation by binding to the androgen receptor." (PMID 28159929, 2017). "Besides, the lately study elaborated that PCGEM1 and PRNCR1, bound successively to the androgen receptor and strongly enhanced both ligand-dependent and ligand-independent androgen-receptor-mediated gene activation programs and proliferation in prostate cancer cells." (PMID 28915709, 2017). "In prostate cancer, NEAT1 and PRNCR1 are key elements of estrogen and androgen signaling, respectively." (PMID 27340923, 2016). "The highly expressed cheRNAs PRNCR1 (also known as PCAT8) and PCGEM1 in prostate cancer can bind to the androgen receptor and mediate the cyclization of the promoters of androgen receptor binding enhancers and their target genes to promote the development of tumors." (PMID 33937246, 2021). "We therefore sought to investigate PRNCR1 and PCGEM1 in prostate cancer." (PMID 24727738, 2014).
prostate carcinoma (continued). "Thus, we conclusively demonstrate that PCGEM1 and PRNCR1 are not prognostic lncRNAs in prostate cancer and we refute suggestions that these lncRNAs interact in AR signaling." (PMID 24727738, 2014). "LncRNA levels are strongly associated with aberrant gene expression that may drive cancer development and progression, such as HOTAIR in non-small cell lung cancer (NSCLC), PRNCR1 (also known as PCAT8) and PCGEM1 in prostate cancer, and MEG3 in cervical cancer and meningiomas." (PMID 25496320, 2014). "Several other genes and ncRNAs at 8q24, such as POU5F1B (previously thought to be a pseudogene), PRNCR1, CASC11 and CCAT2, have also been shown to be overexpressed in prostate cancer and may also play a role in the development or progression of prostate cancer." (PMID 33374332, 2020).
colorectal cancer (10 papers, 2013 to 2025). A primary or metastatic malignant neoplasm that affects the colon or rectum. "The association between PRNCR1 gene polymorphism and the risk of colorectal cancer in patients older than 58 years." (PMID 31487296, 2019). "The association between PRNCR1 gene polymorphism and the risk of colorectal cancer in male patients." (PMID 31487296, 2019). "The association between PRNCR1 gene polymorphism and the risk of colorectal cancer in female patients." (PMID 31487296, 2019). "In the present study, we planned to evaluate the association of PRNCR1 variants with Saudi colorectal cancer progression." (PMID 31487296, 2019). "Genotype frequencies of PRNCR1 gene polymorphism in colorectal cancer tumors located in the rectal area." (PMID 31487296, 2019). "PRNCR1 was reported to be frequently mutated in many types of cancers, such as esophageal cancer, colorectal cancer, and breast cancer." (PMID 31487296, 2019). "The association between PRNCR1 gene polymorphism and the risk of colorectal cancer in patients younger than 58 years." (PMID 31487296, 2019). "LincRNA PRNCR1 has been reported to be involved in prostate carcinogenesis and may play an oncogene role via modulating the androgen receptor, PRNCR1 variants, especially rs1456315, are associated with the susceptibility of prostate and colorectal cancers." (PMID 32523949, 2020). "Relationships of polymorphisms in PRNCR1 gene and colorectal cancer susceptibility." (PMID 31487296, 2019). "PRNCR1 levels in tumors were shown to have diagnostic and prognostic importance, and comparatively higher expression levels of this lncRNA were also found in blood exosomes of patients with pancreatic carcinoma, hepatocellular carcinoma, and colorectal cancer than that of normal controls." (PMID 40538732, 2025). "Our findings suggest that the upregulation of PRNCR1 and its variants is associated with increased risk of colorectal cancer in Saudi patients, indicating that PRNCR1 might be a unique and valuable signature for predicting the risk of colorectal cancer in a Saudi population." (PMID 31487296, 2019). "Therefore, we speculate that rs1456315 could be a regulatory SNP, which regulates the expression of PRNCR1 and contributes to the genetic susceptibility of colorectal cancer." (PMID 31487296, 2019). "Meanwhile, genetic variations in PRNCR1 also had been investigated in gastric cancer and colorectal cancer." (PMID 28159929, 2017). "In addition, numerous colorectal cancer associated lncRNAs, such as CCAT6 (MYCLo-2), CASC8 (CARLo-1), CASC21 (CARLo-2), PRNCR1 (CARLo-3), PCAT2 (CARLo-4), and CASC11 (CARLo-7), have been identified." (PMID 30441811, 2018). "However, the relationship between lncRNA PRNCR1 and development of colorectal cancer was previously unknown." (PMID 31487296, 2019).
gastric cancer (4 papers, 2017 to 2021). A primary or metastatic malignant neoplasm involving the stomach. "The PRNCR1 polymorphisms were also associated with gastric cancer risk among Korean and Chinese Populations." (PMID 31956395, 2020). "Based on this knowledge, in a study, the susceptibility of polymorphisms (PRNCR1: rs7463708, rs7007694, rs16901946, and rs13252298; PCAT1: rs1026411 and rs12543663; CCAT2: rs6983267) in the lncRNAs in the region of 8q24 was investigated to risk of gastric cancer." (PMID 34337048, 2021). "Besides, the PRNCR1 acts as an oncogene in colorectal cancer and gastric cancer." (PMID 31956395, 2020).
prostate tumor (4 papers, 2014 to 2024). "PRNCR1 is known to be associated with androgen receptor (AR)-related gene activation in prostate tumor tissues." (PMID 28380453, 2017). "Incorporation of RNA expression data indicated an inverse association between prostate tumor MYC DNA methylation and PRNCR1 expression in tumor tissue." (PMID 33374332, 2020). "When we incorporated RNA expression data in prostate tumor tissue, we observed significant inverse associations between tumor MYC DNA methylation and expression of the lncRNAs PRNCR1 and CASC11, and a significant positive association with miR-1206 expression." (PMID 33374332, 2020).
colon cancer (1 paper, 2019). "Further, they also reported that the silencing of PRNCR1 inhibited the cell cycle at the G0/G1 stage demonstrating that PRNCR1 stimulates the propagation of colon cancer from epithelial cells, and ultimately might increase the tumor size in patients." (PMID 31487296, 2019).
colorectal tumors (1 paper, 2019). "Genotype frequencies of PRNCR1 gene polymorphism in colorectal tumors located in the colon area." (PMID 31487296, 2019).
osteoarthritis (1 paper, 2022). A noninflammatory degenerative joint disease occurring chiefly in older persons, characterized by degeneration of the articular cartilage, hypertrophy of bone at the margins and changes in the synovial membrane. "LncRNA PRNCR1 has been reported to be involved in LPS-induced inflammation, which contributes to osteoarthritis (OA)." (PMID 35422021, 2022). "PRNCR1 has been reported to promote LPS-induced inflammation, which contributes to osteoarthritis (OA)." (PMID 35422021, 2022).
ovarian carcinoma (1 paper, 2023). A malignant neoplasm originating from the surface ovarian epithelium. "For instance, the promoted effect of lncRNA PRNCR1 on the proliferation, migration, and invasion of ovarian cancer was found to be alleviated by the miR-653-5p/ELF2 axis." (PMID 37069939, 2023).
tongue squamous cell carcinoma (1 paper, 2022). A squamous cell carcinoma that arises from the tongue. "In tongue squamous cell carcinoma (TSCC), the PRNCR1/miR-944/HOXB5 axis promotes the tumor cell proliferation, invasion, and migration, and inhibits apoptosis, while the PRNCR1/miR-944/HOXB5 axis can also promote tumor growth in the SCC-9 xenograft nude mice." (PMID 36077769, 2022).